NOTCH1 (notch receptor 1)
Diseases named in the same sentence as NOTCH1 in open-access papers (continued):
Sharing a sentence is not in itself a finding about the gene and the disease.
glioma (continued). "Upon overexpression, we found that SLUG and truncated TAL1-PP22 reduced GSC growth in vitro, and could thus mediate Notch1 anti-proliferative effects in gliomas." (PMID 34771555, 2021). "Furthermore, distribution of the NOTCH1 and NOTCH2 mutations across grade III gliomas was also significantly dependent on H3-3B expression." (PMID 34771425, 2021). "It is known that Notch-1 promotes nestin expression in glioma cells and inhibits their differentiation, so the involvement of Notch-1 in R2J-GS cell activity would also be of interest to better understand the workings underlying the expression of these markers." (PMID 34638987, 2021). "To further explore this relationship and to evaluate whether there is bidirectional regulation, i.e., Notch1 and Sox2 can themselves regulate SNHG6 in glioma cells, we silenced Notch1 and Sox2 using specific siRNAs against them and measured SHHG6 levels." (PMID 34485294, 2021). "Also, it has been found that miR-146a inhibits glioma growth by directly targeting and stopping the Notch1 pathway activity." (PMID 34722277, 2021). "A role for miR-146 in CSCs has been described in colorectal cancer, where it promotes a symmetric mode of division through the Snail/miR-146a/β-catenin/Numb axis, and in glioma, where it was shown to inhibit neurosphere formation and tumor development by targeting NOTCH1." (PMID 33819341, 2021). "The outcomes showed that TSN could inhibit glioma progression property and induce apoptosis via upregulating the expression of miR-608 and downregulating the expression of miR-608 targets, Notch1 and Notch2, in glioma." (PMID 35140606, 2021). "In addition, in the glioma context, both the Notch1 pathway and SLUG gene expression have been found to be implicated in radio-resistance." (PMID 34771555, 2021). "We also demonstrate that NOTCH1 is an important modulator of TM-network formation, and interference with this pathway leads to a partial cross-compensation between these two prime niches of resistance in glioma." (PMID 33579922, 2021). "Therefore, our results show that TRPM7 regulates Notch signaling consistently through Notch1 signaling in glioma tumorigenesis." (PMID 33381038, 2020). "Therefore, our results indicate that TRPM7 regulates the Notch1 pathway in all glioma cell lines even though gliomas are highly heterogeneous with variation in biological characteristics among different glioma cell lines." (PMID 33381038, 2020). "The frequency of these mutations is perhaps surprising since higher expression of ASCL1, Dll1, Notch1, -3, -4 have been shown to correlate with a higher glioma grade and poorer prognosis, implicating Notch signaling in more undifferentiated and aggressive tumor phenotypes." (PMID 31995621, 2020). "Results show that the percentage of apoptotic glioma cells increased from (17.59 + 5.32) to (19.16 + 6.4)% in the controls compared to those silenced by Notch1; and (14.29 + 3.15) to (18.87 + 5.57)% in TRPM7-wt transfected A172 cells compared to those co-transfected with TRPM7 and siNotch1." (PMID 33381038, 2020). "Interestingly NOTCH1-4 loss-of-function mutations have been identified in 10–31% and 7% of grade II and III glioma tumors, respectively." (PMID 33003595, 2020). "Single (uPA, uPAR) or simultaneous (U2) genetic suppression of this multifunctional system reduces glioma cell invasion by inhibiting NOTCH1 cleavage and mRNA expression, as shown in commercially available (U251 MG) and xenograft-derived glioblastoma cell lines (5310 and 4910)." (PMID 33003595, 2020). "To further determine the difference in TRPM7 and Notch1 expression in glioma cells grown in monolayer and glioma neurospheres, we compared those indexes between glioma cells grown in monolayer and GSC spheres derived glioma cells by performing Western blot analysis." (PMID 33381038, 2020). "Besides, NOTCH-1 has also been elucidated as critical players in several cancers, such as glioma and prostate cancer." (PMID 32655137, 2020).
glioma (continued). "CircNFIX is overexpressed in glioma, and the Notch signaling pathway is considerably upregulated in tumor tissues compared with paired normal brain tissues by acting as a sponge in miR-34a that targets NOTCH1." (PMID 30781524, 2019). "As such, we could surmise that NKAP may function in glioma cells via directly binding to the Notch1 promoter." (PMID 31277684, 2019). "Notch1 promotes glioma cell migration and invasion through □-catenin and NF-κB pathway." (PMID 31477177, 2019). "Interestingly, these CXCR4 positive glioma cell, usually expressed Notch1 both and dispersed in the periphery of the sphere." (PMID 31382985, 2019). "As such, we speculated that Notch1 might be the potential target of NKAP in the regulation of glioma development and progression." (PMID 31277684, 2019). "Furthermore, immunohistochemical (IHC) staining of Notch1 and Hes1 proteins were performed on 35 paraffin-embedded high grade glioma samples (15 cases anaplastic astrocytoma and 20 cases GBM) and 12 control brain samples." (PMID 31382985, 2019). "Here we showed that overexpression of NKAP in gliomas could promote tumor growth by contributing to a Notch1-dependent immune-suppressive tumor microenvironment." (PMID 31277684, 2019). "Overexpression of Notch1 could accelerate glioma cell proliferation and formation of neurosphere-forming stem cells." (PMID 30606241, 2019). "Subsequently, our study demonstrated that Notch1 downregulation could significantly inhibit glioma initiating cell biological behavior including self-renewal invasion and migration in vitro, as well as tumor growth in vivo." (PMID 31382985, 2019). "Given that NKAP promotes glioma cell proliferation and invasion and that Notch1 is a potential target of NKAP, we next investigated whether Notch1 represented a functional link for the biological changes observed in the glioma cells with NKAP deletion." (PMID 31277684, 2019). "Instead of a repressor component, NKAP transactivated Notch1 in the glioma cells." (PMID 31277684, 2019). "Notch1 and Notch2 are highly expressed in glioma cell lines as well as primary human gliomas." (PMID 30606241, 2019). "The presence of GICs has been reported in the U87 and U251 cell lines as well as the fact that Notch1 could maintain glioma cell stemness." (PMID 31382985, 2019). "Although Notch1 plays a vital role in a variety of tumors, most of the clinical trials of Notch1 have showed modest efficacy and only in the initial stage, it is probably due to the complex heterogeneity of glioma and the crosstalk between Notch pathway and other molecules." (PMID 31382985, 2019). "Notch1 signaling is a more complex process in the development of numerous cell and tissue types, including gliomagenesis and progression, and is upregulated in glioma-initiating cells." (PMID 29410396, 2018). "All above experiments demonstrated that si-circNFIX could regulate NOTCH1 to promote glioma progression by sponging miR-34a-5p in vitro." (PMID 30072869, 2018). "CircNFIX could regulate NOTCH1 and the Notch signaling pathway to promote glioma progression by sponging miR-34a-5p via the Notch signaling pathway." (PMID 30072869, 2018). "Furthermore, this study investigated the influence that circNFIX has on glioma progression through the upregulation of NOTCH1 via the Notch signaling pathway by sponging miR-34a-5p." (PMID 30072869, 2018). "Furthermore, the expression patterns of Notch1 were confirmed by Western blotting assay in 4 glioma cell lines (LN229, U87, T98G and U251)." (PMID 30170559, 2018). "Accordingly, the upregulation of Notch1 significantly rescued the glioma invasion behaviour." (PMID 30170559, 2018).
glioma (continued). "Upregulating miR-139-5p in cells inhibits glioma growth and reverses Notch1-induced EMT." (PMID 30170559, 2018). "Few reports could be assessed until now, however, regarding the regulation of miR-139 on EMT in glioma, especially though Notch1." (PMID 30170559, 2018). "Notch1 is markedly overexpressed in glioma and accelerated tumour metastasis, invasion and EMT." (PMID 30170559, 2018). "Knocking down Notch1 in these cells effectively suppressed glioma metastasis, invasion and EMT." (PMID 30170559, 2018). "Our study demonstrated that Notch1 was obviously upregulated in glioma tissues." (PMID 30170559, 2018). "However, the contradictory expression of Notch1 among lower grade gliomas and GBMs confounds our understanding of GBM biology and has made identifying effective therapies difficult." (PMID 29410396, 2018). "This demonstrated that Notch1 and NF-κB(p65) are tightly correlated in glioma." (PMID 29410396, 2018). "For the first time, we showed that miR-139-5p reverses the Notch1-mediated EMT of glioma." (PMID 30170559, 2018). "The results show that how the glioma cell fate transitions are performed by the Notch1 signaling." (PMID 28950865, 2017). "In glioma, γ-secretase inhibitors (GSIs) that suppress Notch pathway enhanced the sensitivity of glioma stem cells to radiation at clinically relevant doses; knockdown of Notch1 or Notch2 sensitized glioma stem cells to radiation and impaired xenograft tumor formation." (PMID 28038467, 2017). "The purpose of this paper is to present a computational model for Notch1 signaling pathway in glioma cell lines and primary human gliomas based on intertwined dynamics with cis-inhibition and trans-activation involving the proteins Notch1, Dll1, Jag1, and Lunatic Fringe." (PMID 28950865, 2017). "However, the model still presents the first step toward the possible reasons of over expression of Notch1 in gliomas cells, e.g., high Fringe expression, which provides us some possible clinic treatment of gliomas, e.g., inhibition of Fringe expression." (PMID 28950865, 2017). "Interestingly, enforced expression of miR-129 or inhibition of Notch-1 increased the expression of E2F7 in glioma cells." (PMID 26824182, 2016). "Forced expression of miR-129 could induce autophagic flux by targetedly suppressing Notch-1 in glioma cells." (PMID 26824182, 2016). "In this study, we demonstrated that hsa-miR-129-5p, hereafter referred to as miR-129 unless particularly stated, could induce autophagy by targetedly suppressing Notch-1 in glioma cells." (PMID 26824182, 2016). "Indeed, we demonstrated that overexpression of miR-129 or knockdown of Notch-1 not only inhibited mTOR activity but also increased Beclin-1 protein levels in glioma cells." (PMID 26824182, 2016). "On the contrary, miR-129 inhibition upregulates the protein level of Notch-1 in glioma cells." (PMID 26824182, 2016). "Notch-1 is critical for the development of normal brain and glioma tissues." (PMID 26824182, 2016). "Although endothelial cells may provide Notch ligands that activate Notch pathway and self-renewal in glioma cancer stem cells, our results demonstrate that laminin secretion by endothelial cells is sufficient to activate Notch1 in SVZ cells." (PMID 28018177, 2016). "Notch-1 is critical in cell fate decisions in the developing nervous system and glioma cells." (PMID 26824182, 2016). "In addition, a markedly negative correlation between the expression of miR-92a-3p and CDH1 and Notch-1 was found in glioma cells and GSCs specifically." (PMID 27801803, 2016). "cAMP promotes the differentiation of rat C6 glioma cells by activating Notch1 expression." (PMID 26563263, 2015). "Overall, the data suggested that lower grade gliomas with IDH mutations and 1p19q co-deletions are biologically distinct and arise from a sequence of IDH mutation and 1p19q deletion, TERT/PI3 kinase activation, and NOTCH1 inactivation." (PMID 26244119, 2015).
glioma (continued). "Therefore, binding of Sp1 to the Sp1-binding site 1 is necessary and sufficient for Notch1-mediated regulation of DR5 promoter activity in glioma cells." (PMID 26469969, 2015). "These in vitro data suggest that Notch1 acts as an oncogene in glioma, which has been confirmed in an intracranial xenograft model, where mice injected with control U251MG cells died sooner as compared to mice that received cells in which Notch1 or Dll1 were downregulated by siRNA." (PMID 25601901, 2014). "Furthermore, nuclear Notch1 staining has been correlated with a better outcome in high-grade glioma subtypes." (PMID 25601901, 2014). "Furthermore, we evaluated the effect of EPCs on HIF-1α, Notch1, Flk1, and p-Flk1 expressions in tumors and cultured C6 glioma cells via EPCs transplantation or EPCs-CM treatment, respectively." (PMID 24722469, 2014). "However, according to other reports, the expression of Notch1 exhibits a positive correlation with glioma progression, and high expression of Notch1 protein has been reported to be an independent predictor of poor survival in glioma." (PMID 25601901, 2014). "Further evidence showed that both Ras and Akt induce Notch1 expression in a mouse glioma model." (PMID 25601901, 2014). "Furthermore, a recent report compared the role of the Notch paralogs Notch1 and Notch2, which displayed opposing effects on the propagation of glioma cells." (PMID 25601901, 2014). "The response of brain tumor cells to the modulation of Notch signaling has been investigated by Purow and colleagues, who demonstrated that the siRNA-mediated knock-down of Notch1 in glioma cell lines led to an increased cell death, decreased proliferation as well as cell cycle arrest." (PMID 25601901, 2014). "As we showed before, HIF-1α, Notch1, and Flk1 may be important factors for C6 glioma cells transdifferentiation." (PMID 24722469, 2014). "Increased expression of Notch1 has been shown to promote EMT in glioma; however, the role of Notch1 in ICC remains unclear." (PMID 23688168, 2013). "For example, it is known that Notch1 can activate Akt in cervical cancer, glioma and leukemia." (PMID 23671619, 2013). "In addition, a recent microarray study identified the overactivation of the Akt and Notch1 signaling pathways as hallmarks of poor prognosis for glioma patients." (PMID 23671619, 2013). "NOTCH1 has been shown to have oncogenic roles in glial tumors and its activation may be triggered by several mechanisms, including rearrangements and activating mutations." (PMID 23955600, 2013). "For instance, overexpression of NOTCH1 promotes the invasive capabilities of glioma cells." (PMID 24143218, 2013). "The exogenous expression of Notch1 in glioma cells increased their migratory and invasive capacity." (PMID 23688168, 2013). "Moreover, merely interfering with either Notch-1 or its ligands can induce apoptosis and inhibit proliferation in a number of glioma cell lines." (PMID 22348397, 2012). "In spite this enhanced expression in glioblastomas, experiments carried out in models of experimental gliomagenesis have shown that EGFR stimulation and PTEN inactivation induces miR-146a expression, that in turn acts as a mechanism limiting glioma development, through NOTCH1 targeting." (PMID 22453030, 2012). "Additionally, expression of the constitutively active intracellular domains of Notch1 or Notch2 is protective while knockdown of Notch1 or Notch2 is sensitizing for glioma TSC exposed to radiation." (PMID 24212632, 2011). "Thus, it has been reported for the synthetic oleanane CDDO-Me, modulation of Akt, NF-kB and Notch1 on gliomas and JNK-mediated DR up-regulation on lung cancer cells." (PMID 19543395, 2009). "Therefore, we hypothesized that PDGF‐D promotes the EMT of glioma cells by activating the NOTCH1 signaling pathway, which is dependent on NF‐κB p65 phosphorylation and nuclear translocation." (PMID 40530904, 2025).
glioma (continued). "The interaction of β-1,4-GalT-V with Notch-1 facilitates its signaling functions, which are essential for cell proliferation and metastasis in different types of cancers, thereby linking aberrant glycosylation events with aggressive tumor behavior, particularly in glioma and breast cancer contexts." (PMID 40869407, 2025). "Furthermore, investigations into the regulatory mechanisms governed by Snail have unveiled its ability to modulate the expression of critical EMT-associated molecules such as E-cadherin, Notch1, vimentin, and MMP-9 in various cancer cell types, including gliomas." (PMID 40575155, 2025). "Furthermore, NOTCH1 knockout human‐derived glioma cell lines were also performed." (PMID 39544152, 2024). "Moreover, flow cycle and apoptosis analysis were further used to explore whether knockout of the Notch1 gene enhanced cycle block and increased cell apoptosis of glioma by TMZ." (PMID 39544152, 2024). "Furthermore, mechanistic exploration revealed that T+A@Glu‐NPs degraded the BRD4 protein, leading to the downregulation of Notch1 gene transcription and the inhibition of the Notch1 signaling pathway, thereby augmenting the therapeutic efficacy of glioma chemotherapy." (PMID 39544152, 2024). "Moreover, it has been shown that NOTCH1 and the Notch1 signalling pathway could be upregulated via circNFIX, resulting in glioma progression." (PMID 37628760, 2023). "Gliomas and medulloblastomas are the most common types of brain tumors; several studies reported that the aberration of Notch components in brain tumors, for example, the overexpression of Notch1, 3 and 4, ASCL1, and Hey1, are highly correlated with a higher grade of glioma and poor prognosis." (PMID 38201528, 2023). "Therefore, we believe that when utilized as a tumor suppressor gene, miR-30c can inhibit EMT and the proliferation, migration, and invasion of glioma cells by directly acting on Notch1 at the posttranscriptional level and that it is a potential diagnostic and prognostic marker." (PMID 36180477, 2022). "However, we have recently shown that glioma cells lacking Notch1 are more aggressive than glioma cells lacking Notch2, despite efficient deletion of both Notch1 and Notch2 floxed alleles." (PMID 36358826, 2022). "Therefore, Notch1 is more important in the pathogenesis of gliomas." (PMID 36180477, 2022). "Moreover, the role of NOTCH1 in glioma cell migration and invasion is well established." (PMID 36359750, 2022). "However, data suggest a controversial role of Notch1 in glioma genesis." (PMID 36627893, 2022). "Thus, our current finding confirms our observation that Notch1 is a stronger tumor suppressor than Notch2 in a PDGF-driven mouse model of glioma and implies that Notch1 could partially compensate for Notch2 loss." (PMID 36358826, 2022). "Therefore, it is reasonable that the crosstalk between Smarcd1 and Notch1 contributes to glioma chemoresistance potentially via the existence of GSCs, and strategies targeting pathways involving GSC to break up TMZ chemoresistance are the latest frontier of current GBM treatment." (PMID 33190170, 2021). "In addition, STAT3 binding to the Notch1 promoter inhibits this signaling pathway and may impede the maintenance of glioma stem-like cells while reducing the expression of glioma stem cell markers CD133, SOX2, and nestin." (PMID 34439159, 2021). "KLF9 could regulate the growth of tumor stem cells through the Notch1 signaling pathway, induce the differentiation of neural bulb cells and suppress the growth of tumor stem cells in glioma extended neural bulb cells, and it was low expressed in clinical glioma tissue samples." (PMID 34612136, 2021). "Finally, there is evidence for dormant GSC populations residing at the invasive front of the tumor, where Jagged1 expressed by nerve fibers could facilitate NOTCH1+CD133+ glioma cell invasion of white matter tracts through a SOX9-SOX2-NOTCH1 feedback loop." (PMID 33076453, 2020).